MOG (myelin oligodendrocyte glycoprotein)
Diseases named in the same sentence as MOG in open-access papers (continued):
Sharing a sentence is not in itself a finding about the gene and the disease.
demyelinating disease (191 papers, 2011 to 2026). A broad group of disorders that affect the myelin sheaths that cover the neurons. "Background and Objective: Myelin oligodendrocyte glycoprotein (MOG) antibody-associated disease (MOGAD) is a significant component of demyelinating diseases in pediatric populations." (PMID 41515652, 2026). "Myelin oligodendrocyte glycoprotein (MOG) antibody-associated disorder (MOGAD) is a central nervous system demyelinating disease in children, frequently induced by infection." (PMID 42255904, 2026). "Myelin oligodendrocyte glycoprotein (MOG) antibody-associated disease (MOGAD) is a category of central nervous system (CNS) demyelinating disorders caused by autoantibodies against MOG." (PMID 39960947, 2025). "This case series describes five patients with diverse clinical presentations of myelin oligodendrocyte glycoprotein (MOG) antibody-associated demyelinating disease." (PMID 41393590, 2025). "Myelin oligodendrocyte glycoprotein antibody-associated disease (MOGAD) is currently recognized as a demyelinating disease of the central nervous system (CNS) mediated by antibodies against myelin oligodendrocyte glycoprotein (MOG-IgG)." (PMID 40703404, 2025). "By contrast, anti-MOG autoantibodies are diagnostic for a separate entity of demyelinating disorder called MOGAD." (PMID 40258140, 2025). "Myelin oligodendrocyte glycoprotein antibody associated disease (MOGAD) is a relatively new disease entity in the field of demyelinating disorders." (PMID 39148657, 2024). "Myelin oligodendrocyte glycoprotein (MOG)-IgG-associated disease (MOGAD) is a relatively uncommon autoantibody demyelinating disorder of the central nervous system (CNS)." (PMID 39062226, 2024). "Particularly, autoantibodies directed against MBP (myelin basic protein) and/or MOG (myelin oligodendrocyte glycoprotein) are implicated in the pathogenesis of MS and other demyelinating diseases." (PMID 39654365, 2024). "Myelin oligodendrocyte glycoprotein (MOG)-IgG-associated disease (MOGAD) is a relatively uncommon autoantibody demyelinating disorder of the central nervous system (CNS) with heterogeneous clinical manifestations and magnetic resonance imaging (MRI) findings." (PMID 39062226, 2024). "Although MOG autoantibody-associated demyelinating diseases generally have a good prognosis, some cases show frequent relapses and residual symptoms." (PMID 36816137, 2023). "EAE induced in macaques by recombinant human MOG presented brain lesions comparable to human MOG autoantibody-associated demyelinating diseases." (PMID 36816137, 2023). "Our data suggest that targeting humoral immunity is a promising therapeutic strategy for demyelinating disorders associated with anti-MOG antibodies." (PMID 36816137, 2023). "This is consistent with the clinical observation that MOG autoantibody-associated demyelinating diseases mostly had a substantial recovery." (PMID 36816137, 2023). "Despite its clinical heterogeneity, MOG antibody-associated disease (MOGAD) has been confirmed as a distinct demyelinating disease." (PMID 36816137, 2023). "Acquired demyelinating diseases associated with MOG-antibodies (MOG-Abs) are collectively referred to as MOG-Ab-associated disease (MOGAD)." (PMID 36401212, 2022). "Myelin oligodendrocyte glycoprotein (MOG) antibody-associated disorder (MOG-AD) is a demyelinating disease of the central nervous system (CNS) that causes neurological dysfunction and potential morbidity." (PMID 35958613, 2022). "We finally validated this result in patients and found that the mRNA level of Map3k9 was decreased in peripheral blood leukocytes from patients with MOG antibody-associated demyelinating disease compared to healthy controls." (PMID 34039371, 2021). "We first detected the upregulation of miR-20a in EAE mice and patients with MOG antibody-associated demyelinating diseases." (PMID 34039371, 2021).
demyelinating disease (continued). "EAE used to be the most widely accepted model for MS; however, in recent years, a growing number of studies have demonstrated that the disease which EAE reproduces is MOG antibody-associated demyelinating disease." (PMID 34039371, 2021). "This is in line with the current knowledge that MOG-antibody associated demyelinating disease is different from MS and cortical demyelination in MS occurs independent of anti-MOG antibodies." (PMID 34170374, 2021). "We will validate the results above in MS patients and compare the results of EAE mice, MS patients, and MOG antibody-associated demyelinating diseases patients in the later studies." (PMID 34039371, 2021). "To determine the importance of the miRNAs in patients, we tested the expression level of the miRNAs in peripheral blood leukocytes from patients with MOG antibody-associated demyelinating diseases." (PMID 34039371, 2021). "The expression of miR-20a was detected by quantitative real-time PCR (qRT-PCR) in EAE mice and patients with MOG antibody-associated demyelinating diseases." (PMID 34039371, 2021). "Autoantibodies targeting the aquaporin-4 (AQP4) water channel protein and the myelin oligodendrocyte glycoprotein (MOG) are associated with a broad spectrum of human central nervous system (CNS) demyelinating diseases." (PMID 32625206, 2020). "MOG-antibody associated disease (MOG-AAD) is a recently recognized demyelinating disorder predominantly affecting children but also occurs in adults, with a relapsing course in approximately 50% of patients." (PMID 32709905, 2020). "MOG-IgG is pathogenic in human demyelinating diseases, and it is a biomarker of autoimmune ON and longitudinally extensive transverse myelitis (LETM)." (PMID 33281728, 2020). "Within the expanding field of MOG Ab-associated demyelinating disorders, there are variations in the analysis of flow cytometry data." (PMID 32117270, 2020). "Identifying the course of demyelinating disease associated with myelin oligodendrocyte glycoprotein (MOG) autoantibodies is critical to guide appropriate treatment choices." (PMID 31545352, 2020). "Studies on the role of Breg cells in the pathogenesis of MOG antibody associated demyelinating diseases remain scanty, which creates the need to explore more potential therapeutic uses of Breg cells." (PMID 32973780, 2020). "In MOG antibody associated demyelinating disease, studies have demonstrated that the Breg cells such as CD19+CD24hiCD38hi and CD19+CD5+CD1dhi B cells are numerically low and functionally impaired." (PMID 32973780, 2020). "Immunoglobulin-G against myelin oligodendrocyte glycoprotein (MOG-IgG) is considered a potential demyelinating disease-associated autoantibody." (PMID 31080435, 2019). "EAE is a CNS demyelinating disease caused by autoreactive T cells directed against myelin proteins like MOG (myelin oligodendrocyte glycoprotein)." (PMID 31632410, 2019). "Several authors agree on pleocytosis and rare oligoclonal bands (OCB) being classic findings in the CSF of children with MOG-ab associated demyelinating disease." (PMID 31163654, 2019). "MOG is expressed within the CNS on the surface of oligodendrocytes and myelin and associated with a range of adult and paediatric demyelinating disorders." (PMID 29992350, 2018). "HLA alleles and MOG antibodies have emerged as two major biomarkers of pediatric and adolescent MS and related demyelinating disorders." (PMID 30595920, 2018). "The three papers in this month’s journal club describe large cohorts of adults and children with MOG-Ab associated demyelinating disease." (PMID 29992350, 2018). "Myelin oligodendrocyte glycoprotein antibody-associated disease (MOGAD) is a demyelinating disorder that may relapse during pregnancy." (PMID 41191199, 2025).
demyelinating disease (continued). "However, there is no consensus on the identification of common MOG epitopes of auto-reactive T-cells and the MOG-ab in demyelinating diseases such as MS, NMOSD, or MOGAD by enzyme-linked immunosorbent assays or by cell-based assays." (PMID 40332104, 2025). "Our results therefore await validation in larger cohorts, and further investigation is needed to determine how well CSF lipids differentiate NMOSD from progressive MS and other neuroinflammatory, demyelinating diseases such as myelin oligodendrocyte glycoprotein antibody-associated disease." (PMID 38844340, 2024). "Autoantibody-associated demyelinating diseases of the central nervous system such as myelin oligodendrocyte glycoprotein-antibody associated disease (MOGAD) and aquaporin 4-antibody positive neuromyelitis optica spectrum disorders (AQP4+ NMOSD) are rare diseases but can cause severe disability." (PMID 36451827, 2022). "A previous study suggested that MOG antibodies may reflect an underlying pathogenic mechanism or even have a beneficial effect in demyelinating disorders and usually respond to immunotherapy." (PMID 35837405, 2022). "Anti-MOG-associated demyelinating disease primarily affects the myelin sheath and oligodendrocytes." (PMID 34279454, 2021). "It would have been much better if we had detected both the CSF and serum levels simultaneously, which could contribute to probing the underlying mechanisms of Th17 cells in MOG-IgG-related demyelinating diseases." (PMID 33281728, 2020). "It is important to identify the role of MOG-Ab-associated diseases in idiopathic inflammatory demyelination, either as a subtype of other demyelinating diseases or as a separate disease entity, not only for further understanding of the pathogenesis but also has practical implications for therapy." (PMID 30426010, 2018). "Recent studies proposed that anti-MOG antibody-associated demyelinating diseases were indeed a clinical spectrum in pediatric patients and that their clinical features were different from those of multiple sclerosis and NMOSD with anti-aquaporin-4 (AQP4) antibody." (PMID 28420330, 2017). "Antibodies against myelin oligodendrocyte glycoprotein are associated with inflammatory demyelinating diseases contributing to acute myelitis in COVID-19 patients and increasing the risk of developing a chronic or recurrent demyelinating disease in convalescing patients." (PMID 36832180, 2023). "Although both AQP4 and MOG antibody ON are antibody-mediated demyelinating diseases of the central nervous system, and both have pathogenic components of inflammation and neurodegeneration, the severity of the disease and the degree of pathogenic factors may differ between them." (PMID 34177778, 2021). "In addition, a possibility has been raised that GFAP levels could discriminate anti‐AQP4 antibody‐seropositive NMOSD from other demyelinating diseases such as anti‐MOG antibody‐associated diseases." (PMID 32495489, 2020). "Furthermore, in a marmoset model of EAE, a tolerization procedure with MOG results in early protection from acute disease but the late onset of a lethal demyelinating disorder, associated with a Th2 shift of myelin-reactive T cells and increased titres of MOG-reactive autoantibodies." (PMID 31205957, 2019). "The patient’s case allows us to analyze the multi-phase, clinically diverse course of MOGAD and, above all, indicates the need to expand the diagnosis of epilepsy towards demyelinating diseases: determination of anti-MOG and anti-AQP4 antibodies." (PMID 40137458, 2025). "Recently, anti-MOG antibodies have emerged as a significant biomarker for distinguishing subsets of demyelinating diseases." (PMID 39789036, 2025). "Most importantly, it indicates the need to extend the diagnosis of epilepsy towards demyelinating diseases: the determination of anti-MOG and anti-AQP4 antibodies in the serum, especially in case of focal seizures." (PMID 40137458, 2025).
demyelinating disease (continued). "These interactions are, however, sufficient to produce demyelinating disease, resulting in clinically measurable motor deficits when HuPBMC mice are immunized with MOG." (PMID 40043135, 2025). "They tested 683 patients (121 children and 447 adults) with demyelinating diseases for anti-MOG antibodies." (PMID 39789036, 2025). "With the continuous advancement and widespread application of detection assays for myelin oligodendrocyte glycoprotein (MOG) antibodies, MOG antibodies (MOG-Abs) are increasingly being identified in a broadened spectrum of acquired demyelinating disorders." (PMID 41208985, 2025). "Myelin-associated glycoprotein (MAG) and myelin oligodendrocyte glycoprotein (MOG) are glycoproteins found in myelin, with MOG often being a target for autoimmune responses in demyelinating diseases." (PMID 39081666, 2024). "The pediatric presentation of MOGAD is more common, and the imaging is more heterogeneous, as patients with other demyelinating diseases are also MOG-IgG positive." (PMID 39728911, 2024). "Patients diagnosed with MOGAD are seropositive for an antibody against MOG and exhibit a variety of symptoms similar to other neuroinflammatory and demyelinating diseases." (PMID 39728911, 2024). "As a target autoantigen in demyelinating disease, MOG-IgG has been clearly established to elicit cellular and humoral immune responses." (PMID 39845958, 2024). "Recently, autoantibodies to myelin oligodendrocyte glycoprotein (MOG), a component of the central nervous system myelin, were identified in a subset of demyelinating diseases." (PMID 36816137, 2023). "To elucidate the role of anti-MOG autoantibodies in human demyelinating disorders, we assessed the effect of autoantibodies on MOG-expressing cells." (PMID 36816137, 2023). "Among central nervous system autoimmune diseases, the age distribution of MOG antibody-associated disease, anti-NMDAR encephalitis, and the central demyelinating disease tends to fall between the lower quartile and the median." (PMID 37407586, 2023). "The autoantibody to myelin oligodendrocyte glycoprotein (MOG), a component of the central nervous system myelin, has been identified in a subset of demyelinating diseases." (PMID 36816137, 2023). "Variable clinical presentations at relapse are highly relevant in children with MOGAD as this is rarely observed in other pediatric demyelinating disorders such as NMOSD and non‐MOG‐Ab associated ON and TM." (PMID 37000895, 2023). "MOG is considered a possible target antigen for antibodies in MS disease models and other demyelinating diseases." (PMID 35159390, 2022). "For example, in some neurodegenerative diseases, some common biomarkers can be found, such as MOG, which is suggested as a potential biomarker for demyelinating diseases such as AD and MS." (PMID 35159390, 2022). "Neurological syndromes associated with MOG- and AQP4-antibodies now appear as two separate demyelinating diseases, characterized by distinct pathophysiology: AQP4-NMOSD is an astrocytopathy while MOGAD currently appears as an oligodendrogliopathy." (PMID 34097296, 2022). "This is mainly due to the overlap of MOG-EM MRI findings with other demyelinating diseases, notably MS and NMO." (PMID 34327021, 2021). "It has substantial overlap with other demyelinating diseases in terms of clinical and radiological features; thus, the diagnosis should always be accompanied by MOG-IgG testing." (PMID 34327021, 2021). "We report a patient with a borderline personality disorder (BPD), which developed NMDAR-E and an overlapping demyelinating disorder with anti-Myelin oligodendrocyte glycoprotein (MOG) -IgG positivity." (PMID 34266413, 2021). "Our analyses provide support for the use of Seldegs, that avoid the generally immunosuppressive effects of current treatments, to treat demyelinating diseases involving MOG recognition." (PMID 33212299, 2021).
demyelinating disease (continued). "Collectively, the developments in characterizing MOG-specific responses have led to a paradigm shift in the understanding of how antibody responses are key players in demyelinating disease." (PMID 33212299, 2021). "Several researchers have suggested that MOG antibody-related demyelinating disease is an independent disease with unique clinical manifestations, radiologic presentations, treatment response, and prognosis, and it differs from other IIDDs." (PMID 34093424, 2021). "Treatment of anti-MOG demyelinating disease consists of a similar approach with steroids or plasma exchange in the acute setting and disease-modifying therapy for the management of relapsing disease." (PMID 34279454, 2021). "Myelin oligodendrocyte glycoprotein (MOG) antibody disease has been recognised as a distinct demyelinating disorder." (PMID 33996312, 2021). "To conclude, this report investigates AQP4- and MOG-specific T-cell reactivities in human individuals presenting with AQP4-Ab and MOG-Ab positive demyelinating diseases." (PMID 32625206, 2020). "B cell studies in MOG-induced demyelinating disease have led to a contradictory literature, in that there is evidence for both pathogenic and regulatory roles, as well as models that require and yet do not require the presence of B cells for EAE." (PMID 32193439, 2020). "MOG is a component of the myelin sheath uniquely expressed in oligodendrocytes in the CNS, which has been described as a potential target of demyelinating diseases." (PMID 33584514, 2020). "One MOG antibody positive case met the clinical/MRI 2015 IPND criteria for a diagnosis of NMOSD, but was considered as a MOG antibody-related demyelinating disease case." (PMID 31636597, 2019). "In this work, computational approaches were implemented in the MOG-antibody 3D complex, considering MOG external domain and MOG immunogenic peptides, aiming structural and dynamic data generation for demyelinating diseases understanding." (PMID 30765742, 2019). "MOG antibody-related demyelinating disease accounts for up to one third of cases of pediatric demyelinating disease, often presenting with acute disseminated encephalomyelitis, a clinical picture that is rare in NMOSD." (PMID 31636597, 2019). "This case was negative for all other cell-based assays for AQP4 antibodies and was confirmed as positive for MOG antibodies by FACS assay and so was not considered to be a case of NMOSD, but rather as a case of MOG antibody-related demyelinating disease." (PMID 31636597, 2019). "The current study provides an in-depth characterization of the human MOG Ab response in a large cohort of paediatric and adult demyelinating disorders." (PMID 31481127, 2019). "From an imaging standpoint, the MRI burden of lesions in the brain and spine has been shown to be extensive in patients with MOG-ab-positive pediatric demyelinating diseases." (PMID 31163654, 2019). "Myelin oligodendrocyte glycoprotein (MOG) antibody-related demyelinating disease is emerging as another antibody mediated inflammatory disorder of the CNS which shares some overlapping features with NMOSD." (PMID 31636597, 2019). "Myelin oligodendrocyte glycoprotein (MOG) has been regarded as a putative autoantigen and autoantibody target in patients with demyelinating diseases for almost three decades." (PMID 30595920, 2018). "Subsequently, anti-MOG antibodies were identified in pediatric demyelinating diseases, including ADEM and clinically isolated syndromes." (PMID 29064441, 2017). "This has been the case for anti-Caspr2 and anti-MOG antibodies in encephalitis and demyelinating disorders, respectively." (PMID 27577085, 2016). "Lastly, myelin-oligodendrocyte glycoprotein (MOG) antibody has recently been found in patients with demyelinating diseases of the CNS, including LETM." (PMID 24779645, 2014). "Myelin-oligodendrocyte glycoprotein antibody (MOG antibodies) was found in various demyelinated diseases." (PMID 25434485, 2014).